DMRT1 (doublesex and mab-3 related transcription factor 1)
Diseases named in the same sentence as DMRT1 in open-access papers:
DMRT1 is named in the same sentence as 46 diseases in open-access papers, as found by Europe PMC text mining. Sharing a sentence is not in itself a finding about the gene and the disease. The quoted sentences say what the papers report.
infertile (8 papers, 2018 to 2026). "Similarly, DMRT1 loss of function has been demonstrated in infertile men while PPARG plays a role in testis fatty acid dysmetabolism in men with impaired spermatogenesis." (PMID 40086448, 2025). "Indeed, when DMRT1 is disrupted in male humans it leads to disorders of sex development, while disrupting this gene in male mice causes infertility." (PMID 37847154, 2023). "Interestingly, even DMRT1 dosage sensibility has been conserved between chicken and rabbits since heterozygous XY DMRT1+/− male rabbits present secondary infertility with an arrest of spermatogenesis around 2 years of age (data not shown)." (PMID 37847154, 2023). "At the same time, we hypothesised DMRT1 to be an interesting candidate gene for male spermatogenic failure and sequenced this gene in around 300 infertile patients with azoo- or cryptozoospermia (sperm concentration below 0.1 mill/ml)." (PMID 29527098, 2018). "Consecutively, in 2013, smaller deletions in DMRT1 were identified in five infertile men with azoospermia but no symptoms of gonadal dysgenesis." (PMID 29527098, 2018). "The phenotypic effect of the downregulation of DMRT1 in pansteatitic Nile crocodiles is not known at the moment, the supression of its expression may lead to infertility in the affected animals, although, this is a subject of further investigation in the future." (PMID 31738794, 2019).
male infertility (8 papers, 2017 to 2024). The inability of the male to effect fertilization of an ovum after a specified period of unprotected intercourse. "At the moment, only three autosomal dominant genes are moderately linked to isolated male infertility: doublesex and mab-3 related transcription factor 1 (DMRT1), kelch like family member 10 (KLHL10) and synaptonemal complex protein 3 (SYCP3)." (PMID 30865283, 2019). "Accordingly, small deletions that affect only several exons of the DMRT1 gene or regulatory variants of DMRT1 are found in patients with milder gonadal dysfunction, such as male infertility." (PMID 28956011, 2017). "The confirmation of father-to-son transmission of a deletion including DMRT1 represents an important point for clinicians dealing with male infertility, even when complete azoospermia is repetitively detected, and must be of hope for a relevant portion of men." (PMID 39259317, 2024). "Regarding the role of the DMRT1 gene, this case represents further evidence supporting its important role in male infertility, confirming the indication to include it among the genes to be investigated in cases of NOA of unexplained cause." (PMID 39259317, 2024). "So far, DMRT1 loss-of-function has been described in two mammalian species and induces different phenotypes: Disorders of Sex Development (46, XY DSD) in men and male infertility in mice." (PMID 37847154, 2023). "However, up to now, for only three genes, i.e., NR5A1, DMRT1, and TEX11, associations with male infertility have been evidenced in independent biological and functional studies." (PMID 31963602, 2020). "Human DMRT1 deletions and microdeletions on the distal part of chromosome 9, where DMRT1 is located, and missense mutations in the DM domain have been associated with Disorders in Sexual Development (DSD), and reported to cause partial or complete 46,XY gonadal dysgenesis and male infertility cases." (PMID 35958734, 2022).
teratoma (8 papers, 2011 to 2024). A non-seminomatous germ cell tumor characterized by the presence of various tissues which correspond to the different germinal layers (endoderm, mesoderm, and ectoderm). "Methylation classifier analysis confirmed the diagnosis of teratoma, and DMRT1 loss and 12p gain were identified by copy number variation analysis, potentially elucidating the cause of growth and malignant transformation of the teratoma." (PMID 38668041, 2024). "Previously genetic alterations in germ cells, including the ter mutation in the Dnd1 gene, loss of Dmrt1, or loss of Pten produced a high incidence of TGCTs (particularly teratomas) in mice." (PMID 22348147, 2012). "Dmrt1 regulates germ cell proliferation in a cell autonomous and dosage dependent manner in mice, and its loss results in an increased incidence of teratomas." (PMID 21672208, 2011). "DMRT1 loss and 12p gain were identified by copy number variation analysis, potentially elucidating the cause of the formation and malignant phenotype of the teratoma." (PMID 38668041, 2024). "We can speculate that in the present case, DMRT1 loss caused differentiation into various tissue types, such as cartilage and bone, leading to the formation of teratoma." (PMID 38668041, 2024). "In addition, defects in the same genes, kit-ligand (KITL) and Dmrt1, dramatically increase the incidence of teratoma in mice and are associated with or predispose humans to the adult TGCTs." (PMID 22348147, 2012). "Although the frequency of spontaneous generation of mGS cells is low (approximately 1 of 30 testes), the simultaneous transfection of GS cells with short hairpin RNA against Dmrt1 and Trp5330, both known suppressors of teratomas, significantly enhances the derivation efficiency." (PMID 34921203, 2021).
germ cell tumor (7 papers, 2013 to 2024). A benign or malignant, gonadal or extragonadal neoplasm that originates from germ cells. "Downregulation of Dmrt-1 was linked to germ cell tumors in mice testicles, while its homolog in humans was implicated in susceptibility to germ cell tumors." (PMID 34205122, 2021). "Furthermore, the DMRT1-related epigenetic landscape is associated with trophoblast competence of the reprogrammed cells and provides a therapeutic target for germ cell tumors." (PMID 34413299, 2021). "Interestingly, the authors found Nanos3 haploinsufficiency to modify the susceptibility of Dmrt1 deficient male mice by elevating the tumor incidence, clearly demonstrating a role of Nanos3 in germ cell tumor development." (PMID 23967156, 2013). "Here, the authors show that in vivo reprogramming using OSKM generates germ cell tumors and drives acquisition of totipotency-like features in somatic cells through DMRT1." (PMID 34413299, 2021). "DMRT1, expressed in primordial germ cells, is known to drive the reprogramming and propagation of tumor cells, which have the capacity to induce pluripotent stem cells, leading to the development of cancer that resembles human germ cell tumors." (PMID 38668041, 2024). "We found that DMRT1 is highly expressed in germ cell neoplasia in situ (GCNIS), a premalignant lesion of various types of testicular germ cell tumors (TGCTs), while it is not expressed in most cancer types." (PMID 34413299, 2021).
gonadal dysgenesis (5 papers, 2013 to 2025). A congenital disorder characterized by the presence of extremely hypoplastic gonads preventing the development of secondary sex characteristics. "Mutations in NR5A1, DMRT1, and MAP3K1 are other leading causes, but together with mutations in the SRY gene, they explain less than 40% of all non‐syndromic forms of 46 XY gonadal dysgenesis." (PMID 40747867, 2025). "DMRT1 is situated in a region of chromosome 9p that has been identified as a source of syndromic and non-syndromic forms of XY gonadal dysgenesis (GD)." (PMID 23555275, 2013). "In addition, patients with partial duplications of Xp (including the NR0B1 gene) and chromosome 9p deletions (involving the DMRT1 and DMRT2 genes) may also present with isolated 46,XY complete gonadal dysgenesis (CGD)." (PMID 28836496, 2018).
Azoospermia (3 papers, 2013 to 2024). Absence of any measurable level of sperm,whereby spermatozoa cannot be observed even after centrifugation of the semen pellet. "Haploinsufficiency of DMRT1 was therefore considered the determining factor in the development of azoospermia in the family by a loss of function mechanism." (PMID 39259317, 2024). "In this family, both patients were diagnosed with NOA and varicocele at the same time: we can hypothesize that the latter is one of the manifestations associated with DMRT1 alterations, and we can also speculate that varicocele may have played an additive role in the development of azoospermia." (PMID 39259317, 2024). "In an independent sample of Han Chinese men, we identified 3 more DMRT1 deletions in 979 cases of idiopathic azoospermia and none in 1,734 controls, and found none in an additional 4,519 controls from public databases." (PMID 23555275, 2013).
Intellectual disability (3 papers, 2018 to 2025). "The five patients in our study affected by DMRT1 deletion or DAX1 duplication had varying severity of intellectual disability, requiring attendance at special schools." (PMID 39936125, 2025). "According to the literature, CER1 and FREM1 have been suggested as responsible for trigonocephaly, DOCK8 has been proposed as a candidate gene for mental retardation and seizures, FOXD4 has been related to speech and language delay, and DMRT1 may play a role in sex reversal." (PMID 36672887, 2023).
female infertility (2 papers, 2021 to 2023). Diminished or absent ability of a female to achieve conception. "EGR1 positively regulates DMRT1 expression through promoter binding in Sertoli cells, but knock-out of this gene can also cause female infertility in mice." (PMID 33857129, 2021). "Furthermore, our data support the potential involvement of DMRT1 mutations in different human pathologies, such as 46, XY DSD as well as male and female infertility." (PMID 37847154, 2023). "However, germ cells failed to undergo meiosis, and follicles did not form in XY and XX DMRT1−/− mutant ovaries, leading to female infertility." (PMID 37847154, 2023).
testicular germ cell tumour (2 papers, 2023 to 2024). "Notably, genomic variants were identified near the DMRT1 locus in testicular germ cell tumours, indicating the potential origin of carcinoma in situ, and the role of DMRT1 for irreversible germline commitment." (PMID 37709822, 2023).
testicular teratoma (2 papers, 2021 to 2024). "Dmrt1 acts as a dose-sensitive tumor suppressor gene in 129Sv mice, and loss of Dmrt1 has been shown to cause a high incidence of testicular teratomas in mice of the 129Sv strain." (PMID 38668041, 2024). "Loss of Dmrt1 on the murine 129/Sv background leads to an over 90% incidence of testicular teratomas, due to a lack of ability to silence regulators of pluripotency." (PMID 34301922, 2021).
Adrenal insufficiency (1 paper, 2013). Insufficient production of steroid hormones (primarily cortisol) by the adrenal glands. "Complete sex reversal in 46,XY males without adrenal insufficiency can also occur in conditions such as Leydig cell hypoplasia or due to mutations in SRY, DHH, SOX9, DMRT1, WNT1, or ATRX." (PMID 23748066, 2013).
asthma (1 paper, 2023). "Dmrt1 is thought to have an influence on sex-specific patterns of childhood asthma, and its expression in testis tissue suggests a potential involvement in hormone regulation." (PMID 37398910, 2023).
Brain atrophy (1 paper, 2025). Partial or complete wasting (loss) of brain tissue that was once present. "Among the four patients with DMRT1 deletion, two had evidence of brain atrophy shown in MRI and experienced motor function development delay and hypotonia, requiring physiotherapy and occupational therapy training." (PMID 39936125, 2025).
embryonal carcinoma (1 paper, 2021). A non-seminomatous malignant germ cell tumor characterized by the presence of large germ cells with abundant cytoplasm resembling epithelial cells, geographic necrosis, high mitotic activity, and pseudoglandular and pseudopapillary structures formation. "Remarkably, Dmrt1 expression led to trophoblastic differentiation in NCCIT, an embryonal carcinoma cell line." (PMID 34413299, 2021).
gonadoblastoma (1 paper, 2018). A mixed germ cell/sex cord-stromal tumor characterized by the presence of large germ cells which resemble seminoma cells and small cells which resemble Sertoli or granulosa cells. "Risk of gonadoblastoma is high when the early stage of Sertoli cell differentiation is disrupted by mutations in SRY, WT1, SOX9, DMRT1, FOG2/GATA4, FGF9 etc.." (PMID 28825592, 2018).
Macrocephaly (1 paper, 2021). Occipitofrontal (head) circumference greater than 97th centile compared to appropriate, age matched, sex-matched normal standards. "Additionally, mosaic duplication involving the DOCK8, DMRT1, DMRT2, DMRT3, and KANK1 genes were observed in patient 2, which may explain the presence of macrocephaly in this patient." (PMID 33455084, 2021).
metabolic syndrome (1 paper, 2023). A cluster of metabolic risk factors for CARDIOVASCULAR DISEASES and TYPE 2 DIABETES MELLITUS. "PIK3R2, STRA8, FLT1, DMRT1, FGF22, NR5A2, and FLT genes were up-regulated in metabolic syndrome after exercise." (PMID 37053002, 2023). "PIK3R2, STRA8, FLT1, DMRT1, FGF22, NR5A2, and FLT were up-regulated and PRDM14, POU5F1, and KDR were down-regulated in metabolic syndrome after exercise." (PMID 37053002, 2023).
premature ovarian failure (1 paper, 2023). "Interestingly in humans, one case involving DMRT1 in premature ovarian failure has been reported." (PMID 37847154, 2023).
Sertoli Cell-Only Syndrome (1 paper, 2025). A type of male infertility in which no germ cells are visible in any of the biopsied SEMINIFEROUS TUBULES (type I) or in which germ cells are present in a minority of tubules (type II). "In cases of Sertoli cell-only syndrome, positive sperm retrieval outcomes have been reported in individuals with DMRT1 variants." (PMID 41401169, 2025).
sexual dysfunction (1 paper, 2020). Disturbances in sexual desire and the psychophysiologic changes that characterize the sexual response cycle and cause marked distress and interpersonal difficulty. "Erβ and Dmrt1 cannot be markers of sexual dysfunction in monitoring the impact of pollutants in a population because their expression may vary during maturation between sexes, and their expression may change at different stages of pregnancy." (PMID 33333984, 2020).
testicular cancer (1 paper, 2018). A primary or metastatic malignant neoplasm that affects the testis. "Indeed, DMRT1 is aberrantly expressed in the testicular cancer precursor germ cell neoplasia in situ (GCNIS) as part of a general dysregulation of the mitosis-meiosis switch in these cells." (PMID 30272154, 2018).
varicocele (1 paper, 2024). A condition characterized by the dilated tortuous veins of the spermatic cord with a marked left-sided predominance. "Finally, since DMRT1 alterations have been associated with NOA and abnormal testicular development, but not specifically with varicocele, further studies are required to validate this issue, as varicocele may have played a crucial role in this case." (PMID 39259317, 2024). "To date, DMRT1 alterations have been associated with NOA and abnormal testicular development, but not specifically with varicocele." (PMID 39259317, 2024).
tumor (13 papers, 2011 to 2026). "In addition, several genes associated with germline tumours, including members of the Nodal signalling pathway and genes associated with germline tumours in human GWAS and other studies, including DMRT1, were expressed in germ cells of MEK1/2 inhibited samples." (PMID 38053127, 2023). "In contrast to a crucial role of DMRT1-mediated reprogramming on GCT-like tumor development, DMRT1 induction promoted trophoblast differentiation of OCT4-expressing PSCs." (PMID 34413299, 2021). "Mechanistically, DMRT1, which is expressed in PGCs, drives the reprogramming and propagation of the tumor cells in vivo." (PMID 34413299, 2021). "DMRT1-mediated reprogramming plays a crucial role in the propagation of GCT-like tumor cells that have the propensity to differentiate into trophoblasts." (PMID 34413299, 2021). "Collectively, these findings indicate that DMRT1-mediated in vivo reprogramming drives propagation of D-OSKM tumor cells, which can give rise to PSCs with expanded differentiation capacity into trophoblasts." (PMID 34413299, 2021). "In addition, 72 h MEKi altered genes associated with germ cell or other tumours, or SSC function including higher Dmrt1 and Sox3 and lower Rhox10 expression." (PMID 38053127, 2023). "Strikingly, however, Dmrt1 KO significantly decreased the tumor area in D-OSKM chimeric mice." (PMID 34413299, 2021). "DMRT1 is a transcription factor distinctively expressed in the gonadal cells, including PGCs, which is in agreement with our findings that D-OSKM tumor cells exhibit PGC-related features." (PMID 34413299, 2021).
cancer (6 papers, 2017 to 2024). A tumor composed of atypical neoplastic, often pleomorphic cells that invade other tissues. "DMRT1 further inhibits SOX2, which is associated with a cancer stem cell state in colorectal cancer." (PMID 34108518, 2021). "DMRT1 is upregulated in nine cancers and also shows strong signals in testicular germ cell cancers in both GeneChip and RNA‐Seq datasets." (PMID 33426787, 2021). "Some of the TFs that were downregulated in NLPs, including Esx1, Bhlhe41, and Dmrt1, have been reported to play critical roles in negatively regulating cancer cell and stem cell growth in other tissues." (PMID 28725177, 2017). "By contrast, induction of Dmrt1 had little effect on cancer cell growth of other cancer types." (PMID 34413299, 2021).
infection (4 papers, 2014 to 2019). The state of being infected such as from the introduction of a foreign agent such as serum, vaccine, antigenic substance or organism. "Six inducing factors, Sry, Sox9, SF1, WT1, GATA4, and Dmrt1, were respectively transduced into mES cells by lentiviral infection according to the experimental design." (PMID 30850007, 2019). "We have previously used RCASBP to globally over-express DMRT1 in chicken embryos, however infection with this virus induces early-stage embryo-lethality." (PMID 25003592, 2014). "mES cells with lentiviral transduction of all the six factors, Sry, Sox9, SF1, WT1, GATA4, and Dmrt1 (mES+Trans) had a relatively less growth rate as compared to those without infection (group mES+MEF and mES+TM4)." (PMID 30850007, 2019).
DMRT1 also shares sentences with these, for which no sentence is quoted: adrenal hypoplasia (1 paper); Atrophy (1); carcinoma in situ (1); cerebral palsy (1); cyst (1); Fanconi anemia complementation group L (1); germ cell cancer (1); mesothelioma (1); muscular atrophy (1); ovarian carcinoma (1); pancreatic cancer (1); schizophrenia (1); seminoma (1); spermatogenic failure (1); squamous cell carcinoma of the lung (1); testicular dysfunctions (1); testicular hypoplasia (1); trigonocephaly (1); Turner syndrome (1); type 2 diabetes mellitus (1); viral infection (1).